MAOA (monoamine oxidase A)
Diseases named in the same sentence as MAOA in open-access papers (continued):
Sharing a sentence is not in itself a finding about the gene and the disease.
depression (continued). "Another possible mechanism of the relationship between depression and NAFLD involves increased monoamine oxidase-A (MAO-A) activity, which has been identified in depressed patients." (PMID 33706839, 2021). "Dysregulation in the monoamine oxidase A (MAOA) activity, which has a substrate selectivity for noradrenaline and serotonin, contributes to the common symptoms of depression and anxiety in this condition." (PMID 33725122, 2021). "Notwithstanding that limitation, this study does correlate miR-15b/miR-92b under-expression and PTGS1 over-expression with MAOA hyperactivity, oxidative stress, and augmented apoptosis of neuron cells in OSA-related depression." (PMID 34829725, 2021). "In silico analysis showed that most flavonoids have high docking scores for monoamine oxidase A (MAOA) and monoamine oxidase B (MAOB), which are two important drug targets in depression." (PMID 35052561, 2021). "Correlation analyses further revealed a significant positive correlation between the relative expression of MAOA mRNA in PBMCs of patients with PIU and the Young's Internet Addiction Test and Self-Rating Depression Scale scores." (PMID 34335325, 2021). "Five important depression targets identified using the network map (GRIN2B, GRIN2A, DRD2, SLC6A4, and MAOA) and twenty-one related active compounds were selected for molecular docking." (PMID 33746756, 2021). "Nefazodone is an anti-depression drug, and the target genes/proteins of herb ingredients such as SLC6A2, ADRB2, MAOA are related to depression disorder." (PMID 33106157, 2020). "The results of our study support the role of anthraquinone, kaempferol, and vanillic acid on MAOA, MAOB, and ESR1 in the etiology of depressive disorder." (PMID 32182911, 2020). "We suggest that the common factor for MAOA and other related genetic variations within the monoaminergic system has a general impact on the social emotion regulation system, which in different studies may be conceptualized as depression, impulsivity, alcohol consumption, aggression and ASB." (PMID 29881923, 2018). "SRY effects on MAOA and RET expression could affect normal synaptogenesis and neurotransmission, and enteric nervous system development, and contribute to pathogeneses of diseases associated with these two genes, i.e. depression/cognitive disorders and Hirschsprung disease respectively." (PMID 28646221, 2017). "A recent study proposed that the anthocyanin extract from blueberries ameliorates depression-like behavior in CUMS by upregulating monoamine neurotransmitter levels and BDNF expression and inhibiting MAOA, which promotes neurogenesis via the ERK/CREB/BDNF signaling pathways." (PMID 36499295, 2022). "Monoamine oxidase A (MAO-A) selectively targets the catalysts of the neurotransmitters of serotonin and norepinephrine and is a pharmacological target in seeking out beneficial agents for the treatment of depression." (PMID 35164803, 2022). "We previously found that MAOA-uVNTR and sexual abuse, but not their interaction, were each associated with higher methylation of the MAOA ROI and current diagnosis of depression in a smaller sample of the young women included in the present study." (PMID 34424394, 2021). "In spite of the previous findings that both MAOA and COMT genes are involved in depression and emotional regulation —which are closely related to NSSI—a dearth of studies has examined the roles that these genes play in the association between environmental factors and adolescent NSSI." (PMID 33807669, 2021). "For the first time, we found that miR-15b-5p/miR-92b-3p mimics could inhibit MAOA activity through directly targeting PTGS1 via NF-κB1/SP1 signaling and may be developed as new drug targets for depression treatment in OSA patients." (PMID 34829725, 2021). "Patients with depression have a high density of monoamine oxidase A, which non-specifically metabolizes monoamines." (PMID 34360469, 2021).
depression (continued). "Monoamine oxidase A (MAO-A) is an enzyme that regulates the levels of monoamine neurotransmitters, such as serotonin, noradrenaline and dopamine and it has been used as a therapeutic target for depression." (PMID 30271325, 2018). "In cancers including breast cancer, although the mechanism remains unknown, altered monoamine oxidase-A (MAO-A) expression and depression correlate with poor outcome." (PMID 29099748, 2017). "Among these, MAOA, COMT, TPH1, and TPH2 have been reported to be associated with depression, but a recent genome-wide association study found no significant genome-wide association, and the best candidates did not involve these pathways." (PMID 21827647, 2011). "A recent imaging study of patients with untreated depression found a high global receptor density for the monoamine oxidase A (MAO-A), which nonspecifically metabolises these neurotransmitters." (PMID 17944926, 2007). "This led to our conclusion that dehydrocostus lactone potentially acts as a monoamine oxidase A inhibitor (MAO-AI), leading to increased availability of neurotransmitters such as serotonin, norepinephrine, and dopamine in peripheral tissue and reduces symptoms of anxiety and depression." (PMID 39263345, 2024). "Hence, the MAOA and MAOB gene polymorphisms seem not to significantly affect depression in PD patients." (PMID 37374342, 2023). "Both 6-FUmb and 8-FUmb, as well as parent Umb, exerted neuroprotective effects by inhibiting monoamine oxidase A (MAO-A), self-amyloid β aggregation, and lipid peroxidation, and could be considered as the multitarget-directed ligands for the treatment of depression." (PMID 34946562, 2021). "Finally, functional effects of two validated miRNAs (miR-15b-5p and miR-92b-3p) on oxidative stress, inflammation, and monoamine oxidase A (MAOA) were examined by a series of in vitro IHR experiments, and their implication in the treatment of OSA-related depression was investigated." (PMID 34829725, 2021). "Thus, miR-92b-3p might play anti-inflammatory, antioxidant, and MAOA-inhibiting roles in the progression of OSA and the development of depression by regulating PTGS1 via NF-κB1/SP1 signaling." (PMID 34829725, 2021).
Anxiety (95 papers, 2008 to 2026). Intense feelings of nervousness, tension, or panic often arise in response to interpersonal stresses. "Significant associations were found between the BDNF rs6265 polymorphism and pain catastrophising, OPRM1 rs1799971 and anxiety, and MAOA rs1137070 and depressive symptoms." (PMID 41460692, 2026). "For example, the gene monoamine oxidase A (MAOA) encodes for an enzyme that impacts serotonergic activity in the central nervous system, leading to increased impulsivity and anxiety." (PMID 33803609, 2021). "In humans and mice, upregulation of MAOA is associated with increased anxiety." (PMID 33999965, 2021). "The purpose of this study was to determine whether anxiety and mood disorders in late-reproductive-stage women are related to the serotonin transporter and monoamine oxidase A gene polymorphisms." (PMID 27614969, 2016). "Specific variants were associated with key psychological traits: BDNF rs6265 with pain catastrophising, OPRM1 rs1799971 with anxiety, and MAOA rs1137070 with depressive symptoms." (PMID 41460692, 2026). "Suppression of SIRT1 is noteworthy in that elevated levels of activity enhance MAOA expression and accelerate serotonin turnover, promoting anxiety-like behaviors." (PMID 41515464, 2026). "Even though resveratrol upregulated SERT and 5-HT3A expression less than SSRIs, it effectively reduced anxiety and restored serotonin levels, likely through the upregulation of monoamine oxidase A (MAO-A) expression." (PMID 40508224, 2025). "BDT alleviates depressive- and anxiety-like behaviors primarily by suppressing MAOA expression, reducing 5-HT oxidative degradation and elevating hippocampal 5-HT bioavailability." (PMID 41471275, 2025). "The physiological pathways of anxiety associated with the expression of BDNF, HTR2C, MAOA, and RGS2 can be affected by miR-22 and the repetitive behavior in heterozygous knocked-out mice can be prompted by the partial loss of miR-137." (PMID 36344488, 2022). "Correlation between presence of rs5906957 in MAOA (P = 0.004) with higher anxiety scale in group B was determined." (PMID 34492034, 2021). "In 5HTT knock-out mouse and rat models, the behavioural outcome is rather different from the MAOA knock-out in that it induces higher anxiety and inhibitory control, combined with reduced aggressiveness." (PMID 20187845, 2010). "The authors also found an increase in cortical tyrosine hydroxylase expression and downregulation of monoamine oxidase-A, indicating a change in monoaminergic pathways that could contribute to anxiety reduction." (PMID 39857431, 2025). "However, they are degraded by MAOA, and it is thought that increased MAOA levels and activity are involved in increased anxiety and other emotions, as well as aggression." (PMID 37242280, 2023). "mao+/− fish present mild impairment in social behavior and anxiety, and thus are a potential tool for studies that aim to assess the developmental and behavioral outcomes of interaction between environmental factors and MAOA/B genotype." (PMID 34881779, 2022). "In addition, it was suggested that SIRT1 regulates anxiety by the de-acetylation of a transcription factor regulating the monoamine oxidase A gene in the brain, which is involved in oxidative deamination of dopamine, norepinephrine, and serotonin." (PMID 34867800, 2021). "Rats were trained on a reversal learning task prior to blood sampling, anxiety assessment, and the behavioral evaluation of selective monoamine oxidase-A (MAO-A) and MAO-B inhibitors, which block the degradation of serotonin (5-HT), dopamine (DA), and noradrenaline (NA)." (PMID 28251298, 2017). "Indeed, saffron inhibits monoamine oxidase (MAOA) enzyme in the synaptic cleft, leading to an increase in serotonin, norepinephrine and dopamine levels which have a pivotal role in the regulation of arousal, mood and anxiety." (PMID 36232902, 2022).
Anxiety (continued). "In addition, it is used as a preventive and therapeutic agent in increased irritability, anxiety, sleep disturbances, and decreased performance, all of which may be owing to its inhibitory effects on monoamine oxidase-A (MAO-A)." (PMID 32707963, 2020). "As the MAOA enzyme degrades serotonin and dopamine, the increased enzyme activity leads to reduced serotonin and dopamine levels in the brain, especially in those regions related to regulation of mood and emotions, and thereby to increased depression and anxiety." (PMID 26509718, 2015). "Other than the length of the MAOA uVNTR polymorphism, additional factors that were associated with attempted suicide in MDD patients included the demographic factors of level of education, age, and marital status, the personality characteristics of extraversion and neuroticism, and anxiety symptoms." (PMID 21605465, 2011). "Monoamine oxidase A (MAO-A) plays an important role in various functions of the brain, such as regulation of mood, anxiety and aggression, and dysregulation of MAO-A is observed in stress-related psychiatric disorders." (PMID 30687104, 2018). "Moreover, the spatial distributions of MAOA, MAOB, COMT, and SLC6A4 on the left side of the network suggested that these genes significantly contributed to the pathogenesis of anxiety." (PMID 38684743, 2024). "On the other hand, MAOA hypomorphic mice do not show anxiety-like responses in the elevated plus maze and the light–dark box." (PMID 34881779, 2022). "The monoamine oxidase A (MAOA)—metabolizing catecholamines such as norepinephrine and serotonin and being a target of potent antidepressants such as tranylcypromine—has been suggested as a key player in the pathogenesis of anxiety and mood disorders." (PMID 32524199, 2020). "In the patient group, at T0 a negative correlation between MAOA methylation and the number of panic attacks was discerned at CpG4 (r=−0.486, P=0.010)." (PMID 27045843, 2016). "In the discovery sample, MAOA methylation increased up to the level of healthy controls along with CBT response (number of panic attacks; T0–T1: +3.37±2.17%), while non-responders further decreased in methylation (−2.00±1.28% P=0.001)." (PMID 27045843, 2016). "The study also demonstrated that in mice SIRT1 increases anxiety by deacetylating the brain-specific helix-loop-helix transcription factor, nescient helix loop helix 2 (NHLH2), which increases its activity on the monoamine oxidase A (MAOA) promoter." (PMID 26509718, 2015).
prostate carcinoma (62 papers, 2009 to 2025). A carcinoma that arises from epithelial cells of the prostate gland. "Monoamine oxidase A (MAOA), which is highly expressed in prostate cancer and associated with increased tumor aggressiveness and poor prognosis, represents another therapeutic target." (PMID 40666095, 2025). "For example, in a mouse model of prostate cancer MAOA knockout mice had reduced risk of invasive cancer and a reduced population of CSCs." (PMID 38635728, 2024). "Conversely, a polymorphism in the MAOA promoter conferring low expression is associated with lower risk of developing prostate cancer." (PMID 33513133, 2021). "Accumulating evidence suggests a significant association of increased MAOA expression and advanced high-grade prostate cancer (PCa) progression and metastasis." (PMID 30974737, 2019). "We previously found that MAOA expression was upregulated in prostate cancers in association with higher Gleason grades, but mechanisms modulating cytotoxic drug effects have not been established." (PMID 25198178, 2014). "MAOA is closely associated with the AR activity and development of prostate cancer." (PMID 37958805, 2023). "In addition, curcumin was found to abrogate cancer associated fibroblast-induced prostate cancer cells invasion by downregulating monoamine oxidase A (MAOA)/mammalian target of rapamycin (mTOR)/hypoxia-inducible factor-1α (HIF-1α) signaling pathway." (PMID 31547193, 2019). "Emerging reports showed that overexpression MAOA is associated with prostate cancer (PCa)." (PMID 28402333, 2017). "To further evaluate the clinical relevance of MAOA and HIF1A, we assessed whether elevated MAOA levels in prostate cancers treated with neoadjuvant chemotherapy associated with increased HIF1A in vivo." (PMID 25198178, 2014). "Monoamine oxidase A (MAOA) plays a significant role in prostate cancer progression and AR signalling." (PMID 41249932, 2025). "NMI inhibited MAOA activity with an IC50 of 3.8 μM in LNCaP-derived C4-2B prostate cancer cells and 5 μM in GL26 glioma cells." (PMID 39904854, 2025). "In prostate cancer cells, monoamine oxidase A (MAOA) enhances the levels of Semaphorin 3C (Sema3C), NRP-1, and Plexin-A2." (PMID 39769452, 2024). "Curcumin inhibits cancer-associated fibroblast-driven prostate cancer invasion, EMT, ROS production, and decreased CXCR4 and IL-6 receptor expression through MAOA/mTOR/HIF-1α signaling." (PMID 38008819, 2023). "Although few studies on MAOA in stromal cells have been performed, it was suggested that the expression of MAOA is increased in stromal fibroblasts of prostate cancer and that this promotes tumor cell growth through the IL-6/STAT3 signaling pathway." (PMID 37509535, 2023). "Clorgyline, which is an MAOA inhibitor, was demonstrated to have antitumor effects against prostate cancer, glioma, and Hodgkin lymphoma." (PMID 37509535, 2023). "We have recently demonstrated the inhibitory effects of kava root extracts and kavalactones in prostate cancer cell lines on MAOA and LSD1 enzymes." (PMID 36979456, 2023). "Contrarily, high expression of MAOA in the normal basal prostatic epithelium and in high-grade primary prostate cancer was found." (PMID 36902343, 2023). "The expression of sema3C, NRP-1, and plexin-A2 is upregulated by monoamine oxidase A (MAOA) in prostate cancer cells." (PMID 37627074, 2023). "CAFs enhanced the EMT process by activating the MAOA/mTOR/ HIF1α signaling axis and enhanced the migration and invasion abilities of prostate cancer cells." (PMID 35589690, 2022). "Higher expression of MAOA mediates hypoxia by increasing reactive oxygen species (ROS) in the tumorigenesis, progression, and metastasis of prostate cancer." (PMID 34209963, 2021). "This suggests that MED19 cooperates with ELK1 to regulate AR occupancy and H3K27 acetylation at MAOA, upregulating its expression and driving androgen independence in prostate cancer cells." (PMID 33513133, 2021).